PTHLH (parathyroid hormone like hormone)
Diseases named in the same sentence as PTHLH in open-access papers (continued):
Sharing a sentence is not in itself a finding about the gene and the disease.
tumor (continued). "The PTHLH mRNA and PTHrP protein levels were downregulated in A549 tumours from 2% Pc-Ex-fed mice." (PMID 35406121, 2022). "The PTHLH-high cells were a distinct minority of the total cells and could be found at low levels in the three tumor sub-types." (PMID 35440032, 2022). "Furthermore, the decrease in α2β1 integrin expression correlated with an increase in the genes PTHLH and the hedgehog transcription factor Gli2, which are involved in tumor-induced osteolysis." (PMID 34199096, 2021). "For example, VEGF, PLGF, MMP‐10, MMP‐3, Angpt2, and PTHLH released from tumor cells in various types of tumors are capable of triggering pulmonary endothelium hyper‐permeability, thereby accelerating extravasation of tumor cells." (PMID 33252861, 2020). "Taken together, calcium, RUNX2, and PTHLH form a positive feedback loop that may increase protein expression of RUNX2/PTHLH axis and promote the in orthotopic tumor growth by an autocrine/paracrine PTHLH manner." (PMID 28120940, 2017). "The function of PTHLH as either a promoter or attenuator of cancer progression might depend on the nature of the processed PTHLH peptides present in the tumour milieu." (PMID 25633981, 2015). "Moreover, PTHLH has been characterized as the essential growth factor exhibiting pleiotropic effects, including tumor cell growth, differentiation, invasion, and death 15,16." (PMID 24861371, 2014). "The qRT-PCR assay demonstrated that, among renal tumor subtypes, the clear cell RCCs presented with a higher incidence of detectable signals of PTHLH (535/542 tumors; 98.7%) compared to the other tumor subtypes (60.5–83.3%) as well as to normal kidney samples (58.8%)." (PMID 24861371, 2014). "However, the regulation mechanism and tumor progression role of PTHLH in HNSCC remains uncertain." (PMID 28120940, 2017). "Therefore data from clinical HNSCC patients also demonstrate that PTHLH might regulate tumor growth through cell cycle regulators, namely, CCNA2, CCNE2, and CDC25A." (PMID 28120940, 2017). "Thus, MMP-3 might promote spontaneous metastasis in 4T1.2 and EO771.LMB tumours in part via proteolytic processing of PTHLH and MMP-9." (PMID 25633981, 2015). "Finally, we examined whether the tumor expression of PTHLH was correlated with the survival of patients with clear cell RCC, who underwent standard nephrectomy." (PMID 24861371, 2014). "The strong correlations between neuropeptides PTHLH, NMB, APLN, and GAST with these neurotrophic factors suggest a coordinated mechanism through which tumor cells recruit and sustain neuronal infiltration." (PMID 40805163, 2025). "To identify the potential role of PTHLH in CHO, we evaluated 59 ICC samples and paired non-tumor tissues from NanFang Hospital." (PMID 29178939, 2017). "In summary, our results reveal that PTHLH expression is a poor prognosis marker in HNSCC patients, and RUNX2-PTHLH axis contributes to HNSCC tumor growth." (PMID 28120940, 2017). "We found that CCNA2, CCNE2 and CDC25A are significantly up-regulated in PTHLH expression Ca9-22 cells and those are also up-regulated in the in Taiwanese (p < 0.01) and TCGA data (p < 0.001) HNSCC tumor." (PMID 28120940, 2017). "Secondly, concordant up-regulation of PTHLH and RUNX2 promoted HNSCC tumor growth, and RUNX2 was stimulated by calcium level." (PMID 28120940, 2017). "Tumor status induced a significant decrease in the expression of FIGF (P < 0.0001), ADIPOQ (P < 0.0001), LEP (P = 0.0009), PTHLH (P = 0.0345) and FOS-like Antigen 1 (FOSL1; P < 0.0001) compared with expression in corresponding non-tumor tissue." (PMID 27857161, 2016). "Of note, marked variations of PTHLH expression signals, from very high to almost undetectable levels, were observed even in the VHL alteration-positive tumor group." (PMID 24861371, 2014). "The tumors removed from these euthanized mice were not larger than tumors removed from the EV and no DOX control groups at the time the last DOXi PTHLH tumor-bearing mice needed to be euthanized (day 56)." (PMID 41315757, 2026).
tumor (continued). "Earlier work implicated PTHrP as a therapeutic target in ccRCC 53, although in our model, genetic ablation of PTHLH did not impede tumor growth." (PMID 40964365, 2025). "Although the serum Ca value is a widely used clinical biomarker for RCC, its actual status together with the tumor expression of PTHLH have not been well verified for each histologic subtype." (PMID 24861371, 2014). "Indeed, several of the identified genes in our study are reported to be involved in angiogenesis, tumor angiogenesis and arteriogenesis, i.e. IL-8, ET-1, CARP, HPTPη, ID1, MGSA, SMAD7, HO-1, RHOB, PTHLH, SERPINH1/HSP47, JAG1, GNA13 and TEAD4." (PMID 16594992, 2006). "Upregulated neuropeptide genes, such as PTHLH, Gastrin (GAST), Secretogranin V (SCG5), Neuromedin B (NMB), and Apelin (APLN), were positively correlated with upregulated neurotrophic factors, which were consistent with their roles in tumor progression and neuroimmune crosstalk." (PMID 40805163, 2025). "Interestingly, PTHLH only fully rescued the tumor growth abilities in Cal-27 cells, but not in SAS cells, after Runx2 knockdown." (PMID 28120940, 2017). "However, the status of serum Ca and tumor PTHLH expression have not been verified using the 2004 World Health Organization (WHO) renal tumor classification." (PMID 24861371, 2014).
cancer (249 papers, 1996 to 2026). A tumor composed of atypical neoplastic, often pleomorphic cells that invade other tissues. "A key transcriptional target of Gli2 is PTHLH, the gene which encodes Parathyroid Hormone-related Protein (PTHrP), an osteolytic factor which is secreted by cancer upon metastasis to the bone." (PMID 37954979, 2023). "PTHrP, an essential paracrine and autocrine ligand encoded by PTHLH, regulates bone homeostasis and the initiation, growth, and progression of various types of cancer." (PMID 35406121, 2022). "PTHLH/PTH1R signaling is aberrantly induced or activated in different cancer types and is associated with poor prognosis." (PMID 29178939, 2017). "In this regard, our pan-cancer analyses suggest that PTHLH is significantly correlated with HIF transcriptional activity in multiple cancer types, including HNSC and LUSC." (PMID 40964365, 2025). "Some report also shows that Emodin can suppress the PTHLH expression in related cancer by suppressing the TCF4/TWIST1‐induced complex." (PMID 37555363, 2023). "PTH and PTHLH share the same PTH/PTHrP receptor but have different roles: PTH primarily regulates the blood calcium level, but PTHLH is involved in many other processes such as chondrocyte growth, mammary gland branching morphogenesis, and cancer." (PMID 36960393, 2023). "PTHLH (parathyroid hormone-like hormone) is reported to be involved in the pathogenesis of cancer cachexia." (PMID 35406121, 2022). "PTHLH is correlated with the pathogenesis of cancer cachexia, which is characterised by WAT browning, skeletal muscle loss, and bone metastasis." (PMID 35406121, 2022). "Mechanistically, the expression of PTHLH in multiple cancers is regulated by various transcription factors and signalling cascades." (PMID 35406121, 2022). "PTHrP, the protein encoded by PTHLH, was shown to be secreted by tumors and trigger browning of adipose tissue in cancer cachexia." (PMID 36428623, 2022). "Although MMP1, MMP10 and PTHLH were mainly up-regulated in the 21 cancer types, the other two members GATM and ARHGEF26, were primarily down-regulated." (PMID 34301206, 2021). "Coupled with the upregulation of PTH1R (parathyroid hormone type 1 receptor) seen in our mouse models, PTHLH likely plays a significant role in cancer cell proliferation, migration, and invasion." (PMID 32290096, 2020). "Later, specific inhibition of EGFR expression and activity was reported to notably reduce PTHLH expression in cancer cell lines." (PMID 31293052, 2019). "To investigate the effect of ICC secreted PTHLH on cancer cell growth, we established an in-vitro PTHLH secretion system." (PMID 29178939, 2017). "After arriving at bone, cancer cell responds to TGFβ stimulation and promotes osteoclast maturation via secretory factors such as PTHLH." (PMID 27996004, 2016). "PTHLH can promote cell proliferation and exert a protective effect against apoptosis; moreover, its expression correlates with the severity of carcinoma." (PMID 27716329, 2016). "According to these results, we assume that the overexpression of PTHLH/PTHrP promotes the cell cycle of cancer cells, resulting in accelerated progression of OSCC." (PMID 25539663, 2014). "Since PTHLH represents a potential therapeutic target in breast and in other types of cancer, we assume that further studies will reveal additional, isoform-specific roles susceptible for pharmacological intervention." (PMID 24324612, 2013). "This gene is intriguing in that it is downstream of RUNX2, a master regulator of bone development and ossification, and a high expression has been correlated to a faster disease progression in a number of cancers (i.e., colon, prostate, breast, head, and neck) due to the overexpression of PTHLH." (PMID 32290096, 2020).
cancer (continued). "Bone resorption releases bone matrix embedded growth factors, such as transforming growth factor beta (TGFβ), insulin-like growth factor 1 (IGF1) and calcium ions, which further fuel cancer cell growth and secretion of PTHLH, thus amplifying and perpetuating the process." (PMID 29988965, 2018). "We propose that when arrested in MS, a “maternal cancer germ cell” may be parthenogenetically stimulated by the placental proto-oncogene parathyroid-hormone-like-hormone, increasing calcium, thus creating a ”female pregnancy-like” system within a single polyploid giant cancer cell." (PMID 36834647, 2023). "Although PTHLH, MMP1 and MMP10 were mainly up-regulated in the 21 cancer types, the rest of the members GATM and ARHGEF26, were primarily down-regulated with a few exceptions." (PMID 34301206, 2021). "Top five up-regulated genes in malignant tumours were COL11A1, SFRP2, LCN2, COL2A1 and H19, while top up-regulated genes in benign tumours were MMP3, MMP1, AREG, PTHLH and SFRP2." (PMID 30517191, 2018). "Similarly, the application of the R-package Survminer revealed the prognostic significance of CK19 at primary diagnosis as well as of other cancer-related (CDH5 and TERT) and EMT markers (FAM83A, PTHLH, and ERBB3) at disease progression." (PMID 34834576, 2021). "The top genes were IL12RB2, PTHLH, and SCL7A11, which are all involved in cancer biology." (PMID 26029238, 2015). "Therefore, therapy agents such as roxithromycin, which has inhibited RUNX2 and PTHLH expression, might prevent the HNSCC proliferation and other PTHLH induced cancer related complications." (PMID 28120940, 2017). "In addition, it is also noticed that SMAD7 overexpression failed to completely block cancer cell TGFβ responses as revealed by SBE activity, osteoclast differentiation and PTHLH induction, implying a SMAD7-independent mechanism for the oncogenic role of miR-182 and the TGFβ response of cancer cells." (PMID 27996004, 2016).
skeletal dysplasia (6 papers, 2015 to 2023). Any Mendelian diseases that affects growth and development of the skeleton. "Several skeletal dysplasias have been described that are associated with disruption of PTHLH functioning." (PMID 33981811, 2021).
PTHLH also shares sentences with these, for which no sentence is quoted: multiple myeloma (13 papers); pseudohypoparathyroidism (11); lymphoma (10); metastatic disease (10); primary hyperparathyroidism (9); bone tumor (8); chondrosarcoma (8); diabetes (8); sarcoidosis (8); Lewis lung carcinoma (7); lung adenocarcinoma (7); metastatic cancer (7); neuroendocrine tumors (7); non-small cell lung carcinoma (7); osteoarthritis (7); renal carcinoma (7); diabetic kidney disease (6); metastasis (6); chronic kidney disease (5); Cushing syndrome (5); Hypercalciuria (5); Hyperglycemia (5); hyperparathyroidism (5); hypophosphatemia (5); insulinoma (5); Kidney Disease (5); Obesity (5); pancreatic neuroendocrine tumor (5); parathyroid adenoma (5); acrodysostosis (4).
A further 204 diseases each share a sentence with PTHLH in 4 papers or fewer.